ADAM10 (ADAM metallopeptidase domain 10)
Diseases named in the same sentence as ADAM10 in open-access papers (continued):
Sharing a sentence is not in itself a finding about the gene and the disease.
tumor (continued). "The important role of ADAM10 in the pathogenesis of HCC is supported by the reduced proliferation, migration and invasion of tumor cells, both in vitro and in vivo, as a result of the downregulation of ADAM10 using an RNA silencing method." (PMID 37185715, 2023). "In order to reveal if the expression of these miRs also negatively correlates with ADAM10 and ADAM17 expression patterns in primary RBs, 15 RB patients’ tumor samples were analyzed." (PMID 36293469, 2022). "While the wide expression of ADAM10 in normal tissues could undermine such an approach, we previously showed preferential binding of our antibody, 8C7, to active ADAM10 which was upregulated in tumours compared to normal tissues, both in mice and in human samples." (PMID 35804938, 2022). "Using miRNA to lower the expression of ADAM10 inhibited the NOTCH pathway, and ultimately up-regulated the sensitivity of malignant tumor cells against tumor drugs." (PMID 36606198, 2022). "The expression of ADAM10 in NSCLC cells (A549, H460 and H520) was much higher compared with its expression level in WI-38, a lung derived non-tumor cell line." (PMID 36606198, 2022). "The ADAM10 augmented expression levels of angiogenesis markers CD31 and VEGF in tumor tissues suggest that ADAM10 promote angiogenesis." (PMID 35551177, 2022). "Different molecules, e.g., monoclonal antibodies, have been developed to inhibit ADAM proteins, rendering ADAM10 and ADAM17 potentially interesting targets in RB tumor therapy." (PMID 36293469, 2022). "While excessive tumor-generated high-affinity EGFR ligands block target engagement by PEPDG278D, aderbasib, an inhibitor of ADAM10 and ADAM17, enables PEPDG278D to exert strong antitumor activity by inhibiting ligand shedding." (PMID 35650607, 2022). "This phenomenon is explained mechanistically by the high expression of MALAT1 in senescent cells, which drives ADAM10 expression through the MALAT1/miR-92a/ADAM10 axis and the release of the ligand MICA/B from tumor cell membranes via hydrolysis." (PMID 35309907, 2022). "Some clinical investigations have reported ADAM10 overexpression in HCC, which correlated with the presence of metastasis, grade, differentiation and size of the tumour." (PMID 35565436, 2022). "Reportedly, some proteases, such as ADAM10 and γ-secretase, induce the membrane-proximal cleavage of CADM1, called shedding, that results in MF-CADM1 formation on tumor cells." (PMID 35805896, 2022). "The correlation of miR-365 with ADAM10 and ADAM17 expression in RB tumor samples appeared to be patient-dependent, but both ADAMs seem to be targeted by miR-365, at least in a subset of RB tumors." (PMID 36293469, 2022). "L1CAM can also be cleaved by the metalloproteinases, ADAM10 and ADAM17, which further results in the release of a 200 kDa soluble ectodomain fulfilling diverse functions in both tumor and immune cells." (PMID 35473609, 2022). "Since ADAM10 and ADAM17 mediate the cell surface cleavage of a large repertoire of substrates that can promote tumor growth, inhibition of their activities is expected to have general tumor inhibitory activities." (PMID 34572138, 2021). "On the other hand, OvCA malignant ascites-derived exosomes display a cargo of tumor progression related proteins, such as L1CAM, CD24, ADAM10, and EMMPRIN, which have been found to correlate with worse prognosis." (PMID 34768926, 2021). "Neurons and OPCs produce NLGN3 by cleavage of ADAM10 sheddase, so the inhibition of this enzyme blocks NLGN3 secretion into the tumor microenvironment and suppresses glioma outgrowth in preclinical models." (PMID 34532286, 2021). "Another pathway implicates the cleavage of N-cadherin by ADAM10′s in cell migration and metastasis, thus treatment of GBM cell lines with an antibody to inhibit ADAM10 decreased tumor growth and migration." (PMID 34638718, 2021).
tumor (continued). "Mechanistic studies further revealed that Tspan5 enhances the expression of active ADAM10, activates Notch signalling, promotes the epithelial–mesenchymal transition (EMT) and triggers the tumour metastasis of HCC." (PMID 33955149, 2021). "In agreement with previous reports, we observed that expression levels of ADAM9, ADAM10, ADAM12 and ADAM17 were increased in tumor versus adjacent non tumor tissues except for ADAM10 that was non-significant, all were associated with poor prognosis." (PMID 33805340, 2021). "In PDAC, a significant contribution of ADAM proteases to tumor progression was reported for ADAM8, ADAM9, ADAM10, ADAM12, and ADAM17." (PMID 33578644, 2021). "It has also been shown that ADAM10 and ADAM17 cleave PD-L1 from the surface of tumor cells and extracellular vesicles." (PMID 34943606, 2021). "Whereas, ADAM10-degraded CD30 impedes the BV efficacy, tumor-derived EVs load bystander cells with CD30 and generate new targets among supporter cells." (PMID 32296414, 2020). "More important, there were elevated expression levels of ADAM10, ADAM17, and ADAM19 in tumor tissues as they became more malignant in terms of pathological grading." (PMID 33043016, 2020). "In tumor specimens collected from CRC patients, there was a positive correlation between BRG1 and ADAM10/17/19." (PMID 33043016, 2020). "ADAM10 cleaves adhesion proteins such as CD44, E-cadherin, N-cadherin and L1 adhesion molecules, whose functions have been correlated with tumour cell migration and invasion." (PMID 30651596, 2019). "Transiently transfected with HuR plasmids in tumour cells obviously eliminated the effect of EGCG‐down‐regulated expression of APP and ADAM10." (PMID 30793483, 2019). "To evaluate the role of HuR in the regulation of APP and ADAM10 by EGCG, we overexpressed HuR in tumour cells." (PMID 30793483, 2019). "Further analysis showed a significant correlation between ADAM-10 overexpression and T stage (P = 0.009) and AJCC TNM stage (P = 0.007), ADAM-17 and larger tumor size (P = 0.007) and AJCC TNM stage (P = 0.002), ADAM-28 and AJCC TNM stage (P = 0.027)." (PMID 29776401, 2018). "This suggests that ADAM10 and ADAM17 are important components of the tumourigenic niche which function to retain cancer stem cells in this niche, promoting self-renewal and tumour recurrence." (PMID 27541285, 2017). "ADAM10 can also generate soluble L1 cell adhesion molecule (L1CAM), which stimulates the migration of tumor cells through binding to the αvβ5 integrin." (PMID 28260841, 2017). "ADAM10 knockdown resulted in increased expression of membrane-bound MICA, decreased production of soluble MICA, and enhanced NK sensitivity of tumor cells." (PMID 27385218, 2016). "We therefore analyzed the constitutive and inducible surface expression of ADAM10 and ADAM17 on a variety of human T cell and tumor cell lines." (PMID 24130797, 2013). "Unexpectedly, we also noted clumps of cells with a chondrocyte-like morphology in ADAM10 KO, but not Wt U251 tumours." (PMID 41226720, 2025). "We therefore used a genetic knockout of ADAM10, from U251 GBM cells by CRISPR/Cas9, to investigate the resulting changes in protein shedding, protein expression, the proliferation of cells in vitro, and tumour xenografts in mice." (PMID 41226720, 2025). "ADAM10 and ADAM17, especially, facilitate the shedding of critical developmental and growth factors and their receptors, as well as immuno-regulatory molecules, hence promoting tumour progression, immune escape, and resistance to therapy." (PMID 40427200, 2025). "ADAM10 inhibitors LT4 and CAM29 were also reported in another study, both of which could enhance the anti-tumour immunity of targeted drugs by increasing the expression of CD30." (PMID 39893499, 2025).
tumor (continued). "The analysis included ADAM10 and ADAM17 concentrations in the tumor tissue and matched surgical margin, as well as selected clinical and laboratory parameters, such as TNM stage according to the 8th edition, the presence of selected comorbidities and SIR parameters: NLR and PLR." (PMID 39940871, 2025). "Authors showed that silencing MALAT1 or ADAM10 could prevent MICA/B release, enhancing NK cell-mediated clearance of senescent tumor cells." (PMID 40496868, 2025). "As Notch signalling is a key pathway regulated by ADAM10, and we detected decreased shedding of Notch ligands and receptors after ADAM10 KO or inhibition in vitro, we also tested the levels of Notch in tumours by Western blot." (PMID 41226720, 2025). "However, it was shown that a higher concentration of ADAM10 and ADAM17 proteins in the tissue from the resection margin correlates with a higher concentration of ADAM10 and ADAM17 proteins in the tissue from the tumor." (PMID 39940871, 2025). "This might mean that the concentration of ADAM10 and ADAM17 directly in the tumor tissue and the surrounding tissue of the surgical margin is more closely correlated than with the concentration of these proteins in the serum." (PMID 39940871, 2025). "Additionally, the correlation between the concentration of ADAM10 and ADAM17 in blood serum and tissue material collected from the tumor and the matched surgical margin in patients operated on for CRC was investigated." (PMID 39940871, 2025). "Inhibiting antibodies of ADAM10/17, CAECAM, or TIM-3, neutralizing sTIM-3, may reinvigorate the T cell response, particularly in anti-PD-1-resistant tumor patients." (PMID 41323263, 2025). "GEPDX ALL-199 and ALL-265 cells with and without ADAM10 KO were mixed at a 1:1 ratio and injected into groups of mice in serial dilutions, and tumor engraftment was analyzed after eight weeks by flow cytometry." (PMID 37422628, 2023). "Interestingly, it has been previously shown that ADAM10 and ADAM17 expression and enzymatic activity are induced by irradiation and that the depletion of these proteases radiosensitize tumor cells." (PMID 37495855, 2023). "Fifteen additional, potential tumour suppressor genes under the control of Notch or modulating Notch downstream functions have been identified in an animal model of HNSCC, including Adam10, Ripk4, EP300, and Ajuba28, which adds emphasis to the tumour suppressor function of Notch signalling." (PMID 37607974, 2023). "ADAM10 and ADAM17 cleave PD-L1 from the surface of tumour and respiratory tract cells." (PMID 37816808, 2023). "In addition, positive ADAM10 expression correlated with TNM stage, size and location of the tumour, depth of invasion as well as lymph node and distant metastases." (PMID 35565436, 2022). "Furthermore, hypoxia can also induce the upregulation of HIF-1 and metalloproteinase domain 10 (ADAM10), leading to decreased NKG2D of NK cells and enabling tumor cells to escape immune monitoring and NK cell-mediated lysis." (PMID 36428567, 2022). "Photo-documentation of CAM tumors developing from inoculated RB cells and quantification of tumor weight and size revealed that ADAM17 single and ADAM10/17 double depleted RB cells develop significantly smaller tumors than control cells, with lower weight and size." (PMID 36293469, 2022). "The mean protein concentration of the ADAM10 was higher in men, both in the tumor and in the margin—these differences, however, were not statistically significant." (PMID 36286024, 2022). "However, further analyses regarding the involvement of ADAM10 and ADAM17 in blood vessel sprouting in RB tumor development are needed to address the question properly." (PMID 36293469, 2022). "ADAM10 and ADAM17 were recently shown to produce different cleavage products of PD-L1 that are shed from the surface of tumor cells, leading to apoptosis of CD8+ T cells and inhibition of anti-tumor immunity." (PMID 36591235, 2022).
tumor (continued). "In the tumor, a higher protein concentration of ADAM10 was detected in this group of patients, but without statistical significance (244.64 vs. 222.18 pg/μg protein; p = 0.45)." (PMID 36286024, 2022). "Expression of ADAM10 and ADAM17 was elevated in all tumor sets analyzed." (PMID 36078095, 2022). "Thus, ADAM knockdown effects on RB tumor formation in vivo confirmed the in vitro effects on cell growth, displaying high effects after ADAM17 and ADAM10/17 and only moderate after ADAM10 knockdown." (PMID 36293469, 2022). "While the non-selective ADAM10 mAb 4A11 bound to both normal colon and tumour epithelial (CD45 negative, EpCam positive) cells, 8C7 preferentially bound to tumour cells, suggesting selective targeting of active ADAM10 in the tumour." (PMID 35804938, 2022). "Consistent with the lack of tumor formation, Arg1809Cys-mutant neurons do not induce Adam10-mediated cleavage and shedding of Nlgn3, a growth factor required for murine Nf1-OPG initiation and growth." (PMID 35589737, 2022). "Galectin-1 forms the hypoxic microenvironment and contributes to the immune evasion of PDAC tumor cells by enhancing HIF activity, promoting the formation of ADAM10, inducing the low expression of NKG2D, and reducing the activity of NK cells in PDAC, which results in poor proliferation of NK cells." (PMID 36428567, 2022). "Importantly, tumors including GBM often secrete NKG2D ligands, for example, through cleavage by ADAM10 and ADAM17 molecules, which often results in decreased surface expression of NKG2D on NK cells and reduced NKG2D-mediated anti-tumor response." (PMID 34926577, 2021). "Since ADAM10-KO cells exhibit high levels of NKG2D ligands, they will be efficiently targeted by NK-mediated cell killing, while maintenance of MITF expression will facilitate a T-cell-mediated anti-tumor response." (PMID 33789714, 2021). "The ADAM10 targets MICA/B have recently been localized intracellularly in normal and tumor tissues." (PMID 34067041, 2021). "Indeed, some ADAMs are expressed in malignant tumors and participate in cancer pathology with ADAM10 and ADAM17 playing a prominent role for this mechanism of tumor immune-evasion by controlling MICA and MICB." (PMID 33789714, 2021). "Shedding of NKG2DL by ADAM10 (and/or ADAM17) in turn impairs tumor-cell lysis by NK cells." (PMID 32117229, 2020). "Using the Cancer Genome Atlas database, we found that higher expression of ADAM9 in tumor tissues was associated with poorer survival of HCC patients (log-rank p = 0.00039), while ADAM10 and ADAM17 exhibited no such association." (PMID 32245188, 2020). "If miR144 has already been proposed as a tumor suppressor by targeting the c-Met oncogene, its role on targeting ADAM10 has not been demonstrated until now in UM." (PMID 32512881, 2020). "Transendothelial tumor cell migration was reduced by about 10% and the irradiation-induced permeability increase was completely blocked in the presence of the ADAM10-specific inhibitor GI254023X, but not GW28064X." (PMID 31619190, 2019). "The permeability of an irradiated endothelial monolayer for macromolecules and tumor cells was analyzed in the presence or absence of the ADAM10/17 inhibitors GI254023X and GW280264X." (PMID 31619190, 2019). "Additionally, both ADAM10 and ADAM17 cleave various other membrane proteins and promote tumor in the cell." (PMID 29560732, 2018). "Recent studies indicate that ADAM10 is involved in the cleavage of a number of proteins such as the NOTCH receptor, its ligand DLL1 and other proteins influencing the metastatic potential of tumor cells through EMT (N-cadherin, E-cadherin, B-catenin)." (PMID 27888801, 2017). "TSPANC8 family proteins (TSPAN5, TSPAN10, TSPAN14, TSPAN15, TSPAN17, and TSPAN33) differentially regulate ADAM10 compartmentalization and thereby selectively promote cleavage of N-cadherin or CD44 which may represent critical steps in tumor cell migration." (PMID 28260841, 2017).
tumor (continued). "ADAM-10 influence on long-term survival or the correlation of ADAM-10 expression with histopathological parameters of the primary tumor was not studied." (PMID 26266086, 2015). "Statistical analysis showed statistically nonsignificant trend of increased ADAM-10 immunoexpression in cancer cells from primary tumor and the presence of distant metastases (P = 0.088)." (PMID 26266086, 2015). "It must be stressed that the researchers did not assess ADAM-10 expression in the whole tumor but only in a section of tumor tissue using tissue microarrays (TMA)." (PMID 26266086, 2015). "This study also demonstrates that the multinucleated giant cell is an angiogenic tumor cell, rather than an osteoclast, and involves ADAM10/Notch1 signaling activation." (PMID 24548763, 2014). "The biopsy samples used in our window study could also pose problems if there is intra-tumor heterogeneity although the IRS scoring used in this study took into account both the percentage and intensity of ADAM10 staining." (PMID 24952873, 2014). "Taken together, these results suggest that what were previously called osteoclast-like multinucleated giant cells are not osteoclasts, but rather angiogenic tumor cells that involve ADAM10/Notch1 signaling activation." (PMID 24548763, 2014). "Using phorbol ester and calcium ionophore as stimuli with documented effects on the regulation of ADAM protease activity and expression, we did not observe a major effect on the surface levels of ADAM10 on tumor cells." (PMID 24130797, 2013). "We investigated the constitutive and inducible surface expression of ADAM10 and ADAM17 on selected tumor cells of different origin and on resting and activated T lymphocytes in a time-frame of three hours without or with stimulation by phorbol ester and calcium ionophore." (PMID 24130797, 2013). "Also, the proteins that were identified as being significantly regulated in the secretomes of both U251 and SW620 cells also correlated with ADAM10 expression in the TCGA datasets of both GBM and CRC tumours, indicating a likely clinical significance across multiple tumour types." (PMID 41226720, 2025). "Regulating the activities of ADAM10 and ADAM17 to inhibit the shedding of MICA/B on cancer cells can significantly promote the degranulation of peripheral, liver, and tumor-infiltrating NK cells and the production of IFN-γ, enhancing the anti-tumor activity of NK cells." (PMID 40563539, 2025). "Analysis of lysates from ADAM10 KO and WT U251 cells revealed changes consistent with those identified above, including downregulation of stem cell markers, such as DCLK1 and ALDH1L2, in keeping with the effects on Notch and Wnt pathway members, and the increased differentiation noted in tumours." (PMID 41226720, 2025). "Therefore, in the current study, we decided to evaluate whether there is a correlation between SIR indices and the concentration of ADAM10 and ADAM17 in tumor tissue and surgical margin." (PMID 39940871, 2025). "A Western blot of immunoprecipitates confirmed the absence of human ADAM10 from KO tumours." (PMID 41226720, 2025). "In the present study, we demonstrate that Kir2.1, an inwardly-rectifying potassium channel, is highly expressed in non-WNT/SHH MBs, which promotes tumor cell invasion and metastasis by recruiting Adam10 to enhance S2 cleavage of Notch2 thereby activating the Notch2 signaling pathway." (PMID 35273141, 2022). "Our experiments show that our ‘8C7 antibody–drug conjugates’ specifically kill cells expressing 8C7-reactive ADAM10, and can inhibit the growth of tumours in mice, without significant side effects, suggesting their potential as a novel approach for targeted cancer therapy." (PMID 35804938, 2022). "In this study, we report that Kir2.1 is preferentially expressed by non-WNT/SHH MBs and contributes to tumor progression by recruiting disintegrin and metalloproteinase domain-containing protein 10 (Adam10) to enhance S2 cleavage of Notch2, thereby activating the Notch2 pathway." (PMID 35273141, 2022).